RHBDF1 (rhomboid 5 homolog 1)
Description:
Regulates ADAM17 protease, a sheddase of the epidermal growth factor (EGF) receptor ligands and TNF, thereby plays a role in sleep, cell survival, proliferation, migration and inflammation. Does not exhibit any protease activity on its own. Regulator of proteosomal assembly by promoting formation of the proteosome assembly chaperone PSMG1-PSMG2 heterodimer, positively regulating proteosome activity.
Synonyms: iRhom1; C16orf8; DIST1; EGFR-RS; FLJ2235; gene-89; gene-90; hDist1
Tractability: Antibody: UniProt predicts a signal peptide or a membrane-spanning region. PROTAC: ubiquitination databases record sites on it.
Gene: Protein-coding gene on chromosome 16 (58,058 to 78,176, reverse strand). Ensembl gene ENSG00000007384.
Subcellular location: Endoplasmic reticulum membrane; Golgi apparatus membrane
Subcellular location (Human Protein Atlas): Vesicles
Gene Ontology:
Molecular function: protein binding; serine-type endopeptidase activity
Biological process: cell migration; cell population proliferation; chaperone-mediated protein complex assembly; negative regulation of protein secretion; regulation of epidermal growth factor receptor signaling pathway; regulation of proteasomal protein catabolic process; regulation of protein secretion
Cellular component: endoplasmic reticulum; endoplasmic reticulum membrane; Golgi membrane; cytoplasm; endomembrane system; membrane
Genetic constraint (gnomAD): Loss-of-function variants: 79 observed, 93.17 expected, observed/expected ratio (o/e) 0.85, 90% interval 0.71 to 1.02. The upper end of that interval is the gene's LOEUF score, 1.02, which puts it in group 4 of 6, group 1 being the genes least tolerant of losing a copy. Missense variants: 1,106 observed, 1,182.7 expected, observed/expected ratio (o/e) 0.94, 90% interval 0.89 to 0.98. Synonymous variants: 511 observed, 483.01 expected, observed/expected ratio (o/e) 1.06, 90% interval 0.98 to 1.14.
Homologues: Orthologues: chimpanzee RHBDF1 (99% identical), mouse Rhbdf1 (96% identical), guinea pig RHBDF1 (95% identical), rat Rhbdf1 (95% identical), dog RHBDF1 (95% identical), rabbit RHBDF1 (95% identical), pig RHBDF1 (95% identical), macaque RHBDF1 (94% identical), tropical clawed frog rhbdf1 (83% identical), zebrafish rhbdf1a (80% identical), zebrafish rhbdf1b (77% identical), Caenorhabditis elegans rom-4 (34% identical), and 2 more. Paralogues in human: RHBDF2 (57% identical), RHBDL3 (11% identical), RHBDL1 (10% identical), PARL (10% identical), RHBDL2 (9% identical).
Diseases named in the same sentence as RHBDF1 in open-access papers:
RHBDF1 is named in the same sentence as 31 diseases in open-access papers, as found by Europe PMC text mining. Sharing a sentence is not in itself a finding about the gene and the disease. The quoted sentences say what the papers report.
breast carcinoma (8 papers, 2018 to 2024). "We show that RHBDF1 deficiency in breast cancer cells results in decreased levels of PERK, pPERK, and peIF2α." (PMID 39420837, 2024). "The RHBDF1 gene shows an association with arsenic-induced skin lesions and is essential to epithelial cancer cell growth and highly expressed in breast cancer." (PMID 37639552, 2023). "The findings support the view that RHBDF1 overexpression, as it is often observed in clinic breast cancer tissues, may facilitate the loss of apicobasal polarity in mammary gland epithelial cells during early stages of breast tumorigenesis." (PMID 39582014, 2024). "Human rhomboid family-1 (RHBDF1) gene is recognized as an oncogene involved in breast cancer development." (PMID 39420837, 2024). "RHBDF1 gene expression is present marginally in normal tissues, but is highly prominent in clinical specimens of breast cancer." (PMID 39582014, 2024). "Silencing the RHBDF1 gene in experimental tumor models leads to apoptosis and autophagy in breast cancer and neck squamous cell cancer cells and inhibition of tumor growth." (PMID 39582014, 2024). "JNK phosphorylates FoxO3 and promotes its translocation into the cell nucleus, and RHBDF1 activates JNK in breast cancer cells." (PMID 39420837, 2024). "Using RT-qPCR analysis, we assessed the mRNA levels ofPERK in MCF-7 MT/R1KO and MDA-MB-231 shCtrl/shR1 breast cancer cells to explore the mechanism by which RHBDF1 stimulates the synthesis of the PERK protein." (PMID 39420837, 2024). "In the present study, we demonstrated that RHBDF1 is able to facilitate PERK expression through the Forkhead box O3 (FoxO3) transcription factor in breast cancer cells." (PMID 39420837, 2024). "We investigated the involvement of RHBDF1 in FoxO3 translocation in breast cancer cells to better understand the mechanism by which RHBDF1 controls FoxO3 transcriptional activity." (PMID 39420837, 2024). "Protein kinase C isoform ζ (PKCζ), which is highly expressed in breast cancer cells, accumulates in the nuclei of human mammary epithelial cells overexpressing human rhomboid family-1 (RHBDF1), an endoplasmic reticulum membrane protein." (PMID 39582014, 2024). "Next, we assessed the protein levels of PERK and its downstream phospho-PERK and phospho-eIF2α inRHBDF1-knockout MCF-7 and 4T1 breast cancer cells overexpressing C-terminal HA-tagged RHBDF1." (PMID 39420837, 2024). "Human rhomboid family 1 (RHBDF1) was significantly elevated in clinical specimens of invasive ductal breast carcinoma and silencing RHBDF1 with siRNA resulted in apoptosis in breast cancer cells and autophagy in head and neck squamous cancer cells." (PMID 30286765, 2018). "RHBDF1 deficiency leads to decreased JNK-mediated FoxO3 translocation into the cell nucleus, resulting in a reduction in PERK and its downstream proteins pPERK and peIF2α in breast cancer cells." (PMID 39420837, 2024). "These protein levels can be restored in RHBDF1-deficient breast cancer cells by artificial overexpression of RHBDF1 but not IRE1 or ATF6." (PMID 39420837, 2024). "RHBDF1-facilitated nuclear translocation of PKCζ is critically responsible for the dismantlement of epithelial cell apicobasal polarity, and thus may serve as a target in the development of therapeutic approaches against early stages of breast cancer." (PMID 39582014, 2024). "We created a plasmid of RHBDF1 tagged with C-terminal HA, transfected it temporarily into MCF-7 breast cancer cells, and measured the protein levels of ER stress sensors in the cells to examine the impact of overexpressing RHBDF1." (PMID 39420837, 2024). "To investigate the role of RHBDF1 in the UPR, we determined the protein levels of ER stress sensors inRHBDF1-knockout MCF-7 and 4T1 breast cancer cells." (PMID 39420837, 2024). "We initially determined the connection between RHBDF1 and JNK in human breast cancer cells to support this hypothesis." (PMID 39420837, 2024).
breast carcinoma (continued). "We also examined the protein levels of FoxO3 and phospho-FoxO3 in breast cancer cells lacking RHBDF1." (PMID 39420837, 2024).
brain hemorrhage (3 papers, 2020 to 2025). "Why does RHBDF2 not rescue multiorgan pathology, including brain hemorrhage and cardiac fibrosis, in Rhbdf1-null mice?" (PMID 34477920, 2021).
Alzheimer disease (1 paper, 2022). A progressive, neurodegenerative disease characterized by loss of function and death of nerve cells in several areas of the brain leading to loss of cognitive function such as memory and language. "The abnormal expression of RHBDF1 was reported in various diseases including cancer, systemic inflammation diseases, Alzheimer’s disease, etc." (PMID 36034446, 2022).
fibrosis (1 paper, 2021). the formation of excess fibrous connective tissue in an organ or tissue in a reparative or reactive process. "In particular, the cardiac fibrosis observed in Rhbdf1-null mice resembles the heart enlargement displayed by Hbegf-null mice, and the eyelids open at birth (EOB) observed in Rhbdf1:Rhbdf2 double KO mice resembles the EOB phenotype displayed by Hbegf and Tgfa double null mice." (PMID 34477920, 2021).
Left atrial enlargement (1 paper, 2020). Increase in size of the left atrium. "Additionally, P21 Rhbdf1−/− mice displayed left atrial enlargement with left ventricular hypertrophy, which is reflected in the higher heart weight/body weight ratio in these homozygous mice compared to heterozygotes." (PMID 32646486, 2020).
melanoma (1 paper, 2025). A malignant, usually aggressive tumor composed of atypical, neoplastic melanocytes. "For example, glycolysis inhibition due to human rhomboid family-1(RHBDF1) deficiency has been reported to enhance the efficacy of immunotherapy in murine melanoma models." (PMID 40046050, 2025).
Parkinson disease (1 paper, 2023). A progressive degenerative disorder of the central nervous system characterized by loss of dopamine producing neurons in the substantia nigra and the presence of Lewy bodies in the substantia nigra and locus coeruleus. "RHBDF1 has been implicated in neurological disorders including Alzheimer’s and Parkinson’s diseases, in addition to cancer, inflammation, and skin diseases." (PMID 37639552, 2023).
cancer (11 papers, 2011 to 2026). A tumor composed of atypical neoplastic, often pleomorphic cells that invade other tissues. "Despite the clear biological importance of RHBDF1, the precise molecular mechanisms and the physiological targets of RHBDF1 underlying the multiorgan pathology and anti-cancer effects resulting from RHBDF1 deficiency remain to be investigated." (PMID 34477920, 2021). "The Rhbdf1 gene encodes RHBDF1 and has been implicated as playing a key role in growth and development, inflammation, and cancer." (PMID 32646486, 2020). "The various and important functions of RHBDF1 make this protein an attractive subject for cancer research." (PMID 39582014, 2024). "Fluorescent immunostaining showed that both PKCζ and RHBDF1 protein levels were higher in cancer tissues." (PMID 39582014, 2024). "Human rhomboid family 1 protein (RHBDF1), also known as inactivated rhomboid 1 (iRhom1), is an ER-resident membrane protein that plays a substantial role in cancer development." (PMID 39420837, 2024). "Nevertheless, the iRhoms RHBDF1 and RHBDF2 have been implicated in neurological disorders including Alzheimer’s and Parkinson’s diseases, as well as in cancer, inflammation, and skin diseases." (PMID 34477920, 2021). "Many studies have shown that RHBDF1 plays a key role in cancer progression, chemotherapy resistance, and poor prognosis, but the underlying molecular mechanism remains unclear." (PMID 39420837, 2024). "RHBDF1 gene over expression may have a role in tumorigenesis and prompted us to investigate the role of RHBDF1 in the early stages of cancer development." (PMID 37639552, 2023). "So, we further analyzed the methylation levels of these genes in pan-cancer, and we found that most of them, such as SPP1, RHBDF1, and NSMCE2, were significantly demethylated, which was consistent with the high expression of these genes specifically in tumors." (PMID 37723560, 2023). "Additionally, when cancer cells were cultured in the presence of the ER stress inducer thapsigargin (TG), the phospho-PERK protein level increased gradually in MT- or shCtrl-treated control cells but not in RHBDF1-deficient cells." (PMID 39420837, 2024).
tumor (7 papers, 2019 to 2025). "RHBDF1, an oncogene protein, is critically involved in various biological processes in the tumor microenvironment." (PMID 39420837, 2024). "RHBDF1 expression is diminished in normal breast tissues but highly elevated in tumor tissues, which is strongly correlated with increased disease progression, metastasis, poor prognosis, and poor response to chemotherapy." (PMID 39420837, 2024). "In a recent study, we also found that RHBDF1, another member of the proteolytically inactive rhomboid, affected tumor immune microenvironment, through a promotion of endothelial-mesenchymal transition and tumor fibrotic stroma growth." (PMID 34736454, 2021).
RHBDF1 also shares sentences with these, for which no sentence is quoted: colitis (2 papers); head and neck cancer (2); bacterial infection (1); cardiac disease (1); cardiac hypertrophy (1); cardiomyopathy (1); cervical cancer (1); colon cancers (1); colorectal cancer (1); esophageal cancer (1); glioma (1); head and neck squamous cell carcinoma (1); Huntington disease (1); invasive ductal breast carcinoma (1); left ventricular hypertrophy (1); liver cancer (1); neuroblastoma (1); neurological disorders (1); ovarian carcinoma (1); pancreatic cancer (1); triple-negative breast carcinoma (1); tylosis (1).